VAV3 (vav guanine nucleotide exchange factor 3)
Diseases named in the same sentence as VAV3 in open-access papers (continued):
Sharing a sentence is not in itself a finding about the gene and the disease.
prostate carcinoma (12 papers, 2008 to 2021). A carcinoma that arises from epithelial cells of the prostate gland. "This approach allowed us to advance our understanding of the possible importance of Vav3 as an efficacious therapeutic modality for prostate cancer beyond its commonly described associations with cell morphology and transformation." (PMID 23566222, 2013). "PCAT-1 promotes proliferation through the oncoprotein Myc, while VAV3 regulates AR activity to stimulate growth in prostate cancer." (PMID 33596994, 2021). "Vav3 has been extensively studied in prostate cancer, being detected in prostate and androgen-independent prostate cancer cells." (PMID 32322580, 2020). "In support, siRNA silencing of RAC/CDC42 regulating GEFs, such as PIP3-dependent Rac exchanger 1 (PREX1) and vav guanine nucleotide exchange factor 3 (VAV3), can significantly reduce prostate cancer cell proliferation and migration in vitro." (PMID 33105713, 2020). "One such GEF is VAV3, which is overexpressed in androgen independent prostate cancer cells and tissues, and up-regulates AR activity in prostate cancer cells." (PMID 30558664, 2018). "Recently, the overexpression of a Rac1 activator protein (14-3-3 protein zeta) and several GEFs (VAV3, P-Rex1) was identified in prostate cancer." (PMID 24848679, 2014). "Vav3 enhances androgen receptor (AR) activity during progression to androgen independence in prostate cancer." (PMID 23566222, 2013). "Our observations support the view that the PI3K/Akt pathway, which is activated by Vav3, is mainly involved in AR activity in prostate cancer development and progression." (PMID 23566222, 2013). "The present study describes a potentially useful approach of utilizing the combination of docetaxel and si-Vav3 to enhance the apoptosis of prostate cancer cells under chronic hypoxia." (PMID 23566222, 2013). "Another oncogene, VAV3, known to regulate cell growth and androgen receptor activity in prostate cancer, also showed a significant increase with LH addition." (PMID 21711548, 2011). "VAV3, an oncogene involved in development and progression of prostate cancer, is up-regulated in tumors that metastasized." (PMID 19356222, 2009). "Recently, we and others found that Vav3 oncogene is overexpressed in androgen-independent prostate cancer cells, enhances androgen receptor (AR) activity, and stimulates androgen-independent growth in prostate cancer cells." (PMID 18518979, 2008). "Our previous study revealed that Vav3 oncogene is overexpressed in human prostate cancer, activates androgen receptor, and stimulates growth in prostate cancer cells." (PMID 18518979, 2008). "Previous studies from our group have demonstrated that Vav3 is overexpressed in human prostate cancer and potentiates AR signaling." (PMID 18518979, 2008). "Within the down-regulated gene set, we note a number of genes that have previously been associated with increased proliferation in prostate cancer; these include kallikrein 2 (KLK2), long non-coding RNA prostate cancer associated transcript 1 (PCAT1), Vav guanine nucleotide exchange factor 3 (VAV3)." (PMID 33596994, 2021). "Therapy targeting Vav3 in combination with docetaxel may have practical implications for managing castration-resistant prostate cancer." (PMID 23566222, 2013). "This approach may provide a novel strategy for the treatment of HRPC, particularly advanced prostate cancer in which the Vav3 signaling pathway is activated." (PMID 23566222, 2013). "That is, prostate cancer under chronic hypoxia may reflect the androgen independent state with Vav3 overexpression." (PMID 23566222, 2013). "We hypothesized that Vav3 may be a key therapeutic target molecule in the regulation of prostate cancer growth and survival under chronic hypoxia." (PMID 23566222, 2013). "More importantly, Vav3 is overexpressed in 32% of human prostate cancer." (PMID 18518979, 2008). "Consequently, higher Vav3 expression was correlated with prostate cancer metastasis and recurrence." (PMID 32322580, 2020).
prostate carcinoma (continued). "However, further work is required to elucidate the functional difference between nuclear and cytoplasmic VAV3, which is reminiscent of the results for PAK1 and could be linked to the activation of the androgen receptor, as previously shown in prostate cancer." (PMID 24886537, 2014). "Therefore, we hypothesized that Vav3 has an important role in regulating the growth and survival of prostate cancer cells under hypoxic conditions and that it is a novel therapeutic target for the treatment of HRPC." (PMID 23566222, 2013). "Deeper examination found the common thread linking down-regulated genes was involvement in proliferation, including several known to increase prostate cancer proliferation (KLK2, PCAT1 and VAV3)." (PMID 33596994, 2021). "A number of RhoGEFs are overexpressed in prostate cancer, including Rac1 GEF P-Rex and Vav3 GEF for RhoA, Rac and CDC42, and are responsible for promoting metastasis and castration resistant prostate cancer (CRPC) by regulating androgen receptor (AR) activity." (PMID 30558664, 2018). "In summary, this study demonstrated that Vav3-mediated signaling converges with PI3K/Akt, ERK, and AR signaling pathways in support of the growth and survival of prostate cancer cells under chronic hypoxia." (PMID 23566222, 2013). "The levels of Vav3, a Rho GTPase guanine nucleotide exchange factor (GEF), are elevated in human prostate cancer specimens, and they increase during the progression of prostate cancer to androgen independence by enhancement of AR transcriptional activity." (PMID 23566222, 2013). "Silencing other PI3K-dependent Rac-GEFs expressed in prostate cancer cells, namely Tiam1, Vav2 or Vav3, also failed to reduce Rac1-GTP levels in PC3 cells." (PMID 32092966, 2020). "In addition, although the number and function of downregulated genes seemed to be less relevant than those upregulated, however we have identified that some of them also appear downregulated in prostate cancer (DST; VAV3; PLK3HH2; ITG6B; PPM1L)." (PMID 27732959, 2016). "Vav3 also potentiates EGF activity for cell growth and AR activation in prostate cancer cells." (PMID 18518979, 2008). "In addition, docetaxel plus si-Vav3 exhibited no toxicity in mice, which makes it an attractive and safe therapeutic strategy in future clinical application to treat prostate cancer." (PMID 23566222, 2013).
glioma (10 papers, 2013 to 2024). A benign or malignant brain and spinal cord tumor that arises from glial cells (astrocytes, oligodendrocytes, ependymal cells). "Vav 3 guanine nucleotide exchange factor (VAV3) has been identified as upregulated in glioma-initiating cells, with its overexpression associated with crucial processes like apoptosis, metastasis, and tumor growth." (PMID 39861688, 2024). "Our study allowed us to identify the four-gene signature (CFH, GALNT3, SMC4, and VAV3) associated with the overall survival of glioma TCGA-LGG patients." (PMID 36539408, 2022). "Moreover, comparative analysis of the transcriptome program of the ICD-based DC vaccine with transcriptome data from the TCGA-LGG dataset identified a four-gene signature (CFH, GALNT3, SMC4, VAV3) associated with overall survival of glioma patients." (PMID 36539408, 2022). "In contrast, Vav3 expression is localized to the glioma cells and Vav3 was shown to mediate exchange for Rac1 in the promotion of glioma cell migration." (PMID 24109588, 2013). "E2F7, PTX3, and VAV3 have been reported as oncogene in many kinds of tumors especially in glioma." (PMID 34222249, 2021). "NOS2 and VAV3 stimulate glioma-initiating cell proliferation and tumour growth in xenograft models." (PMID 29152145, 2017). "The Rho family GEFs, VAV3 and Trio, regulate the invasive phenotype of glioma cells, and a recent study identified the two GEFs, Ect2 and Trio, as activators of various Rho GTPases including cdc42 and Rac1 downstream of Tweak and as regulators of cell migration." (PMID 25682201, 2015). "Vav1 and Vav3 have independently been shown to be overexpressed in patients with high-grade gliomas; Vav1, however, is overexpressed in peritumoral and perivascular, non-neoplastic astrocytes and thus its role may be related to cross-talk between the microenvironment and glioma cells." (PMID 24109588, 2013).
gastric cancer (8 papers, 2010 to 2025). A primary or metastatic malignant neoplasm involving the stomach. "Xie and collaborators describe a potential role of HuR in Vav3 mRNA stability by measuring Vav3 expression after HuR silencing in gastric cancer cell lines." (PMID 36602863, 2023). "It has been proposed that Vav3 overexpression in gastric cancer is mediated by increased mRNA stability." (PMID 36602863, 2023). "Recent studies showed that VAV3 expression is increased in breast, prostate, and colorectal cancer, and VAV3 promoted cell metastasis in gastric cancer." (PMID 31959200, 2020). "Our previous work demonstrated that VAV3 overexpression could be a useful marker for predicting the outcome of gastric cancer patients." (PMID 25791293, 2015). "For all of our validated genes of interest (VAV3, TWIST1 and DKK3), it has previously been established that the level of the mRNA expression is representative for its protein level, in pulmonary fibrosis, gastric cancer and various cell lines." (PMID 20976069, 2010).
pancreatic cancer (5 papers, 2009 to 2025). "Knock down of VAV3 and GPM6A in pancreatic cancer cell lines desensitized the cells to gemcitabine and AraC." (PMID 19898621, 2009).
acute lymphoblastic leukemia (4 papers, 2018 to 2025). Leukemia with an acute onset, characterized by the presence of lymphoblasts in the bone marrow and the peripheral blood. "We used cellular, mouse, and humanized models of RAC-dependent BCR-ABL1-driven and Ph-like acute lymphoblastic leukemia to identify VAV3, a tyrosine phosphorylation–dependent RacGEF, as the target of the small molecule IODVA1." (PMID 34711926, 2022). "In the present study, we demonstrate that Vav3 becomes unexpectedly upregulated and activated in the nucleus of both human and murine lymphoblastic leukemia progenitors upon expression of BCR-ABL." (PMID 35650206, 2022). "Some of these genes have already been shown to play a role in hematologic malignancies, including CLL (Pim-2, Met, Rgs16, Ccdc88a, Zcchc18, Clip3), diffuse large B cell lymphoma, follicular lymphoma (Vav3), acute lymphoblastic leukemia (ALL) (Itm2a, Chst1) or acute myeloid leukemia (AML) (Chd3)." (PMID 30271400, 2018). "We have previously shown that genetic deletion of Vav3, but not Vav1 and Vav2, delays BCR-ABL-induced lymphoblastic leukemia and increases the therapeutic vulnerability during TKI treatments." (PMID 35650206, 2022).
breast tumors (4 papers, 2008 to 2014). "Complementarily to the germline association study, we assessed a series of 29 breast tumors, which had been collected by biopsy after endocrine therapy, for VAV3 expression by immunohistochemistry." (PMID 24886537, 2014). "The statistical analysis of association of Vav3 overexpression with poorly differentiated breast tumors failed (p > 0.05), possibly due to the small number of poorly differentiated tumor specimens." (PMID 18518979, 2008).
colorectal cancer (4 papers, 2014 to 2022). A primary or metastatic malignant neoplasm that affects the colon or rectum. "We identified four putative cancer genes (RWDD1, NCF1, PLEK, and VAV3), whose gene expression profiles were associated with overall poor survival rates in melanoma, lung, or colorectal cancer patients." (PMID 25360158, 2014). "Using a statistical framework, we identified four putative cancer genes (RWDD1, NCF1, PLEK, and VAV3), whose expression profiles were associated with overall poor survival rates in melanoma, lung, or colorectal cancer patients." (PMID 25360158, 2014).
endometrial cancer (4 papers, 2018 to 2025). Primary or metastatic malignant neoplasm involving the endometrium (mucous membrane that lines the endometrial cavity). "Guanine nucleotide exchange factor VAV3, which was 2.81-fold elevated after ESR2 knockdown, has been reported to be an ER-coactivator and oncogene and to be overexpressed in endometrial cancer." (PMID 31357971, 2019). "Because all Vav1, Vav2, and Vav3 were detected by RT-PCR in our endometrial carcinoma cell lines (data not shown), functional compensation may have occurred." (PMID 29872505, 2018).
glioblastoma (4 papers, 2012 to 2020). The most malignant astrocytic tumor (WHO grade IV). "We also have identified roles for the Rho family GEFs Trio and Vav3 in the invasive behavior of glioblastoma cells." (PMID 22966858, 2012). "Previous work has identified roles for the Rho family guanine nucleotide exchange factors Trio and Vav3 in glioblastoma invasion." (PMID 22966858, 2012). "The expression of the three GEFs Ect2, Trio, and Vav3 is elevated in the glioblastoma as compared to lower-grade glioma, and the depletion of any of the three is sufficient to reduce migration and invasion of glioblastoma." (PMID 32089990, 2020).
hypothyroidism (4 papers, 2012 to 2024). Abnormally low levels of thyroid hormone. "VAV3 is involved in immune function, and FOXE1 and PTPN22 have previously been associated with hypothyroidism." (PMID 22493691, 2012). "Similarly, polymorphisms in the listed genes VAV3, SH2B3, FOXE1 and PTPN22 were identified in the 23andMe database to be associated not only with hypothyroidism but also with other autoimmune diseases." (PMID 38919955, 2024).
non-small cell lung carcinoma (4 papers, 2020 to 2023). A group of at least three distinct histological types of lung cancer, including non-small cell squamous cell carcinoma, adenocarcinoma, and large cell carcinoma. "As shown in our previous study, the LINC01234-miR-340-5p/miR-27b-3p-VAV3 axis plays important roles in the progression of non-small cell lung cancer (NSCLC)." (PMID 34327141, 2021). "Activation of VAV3 can promote tumor metastasis, in non-small cell lung cancer." (PMID 36950136, 2023).
Obesity (4 papers, 2013 to 2023). Accumulation of substantial excess body fat. "The SNS hyperactivity is also the original cause of post-receptor insulin-like state and the obesity-independent metabolic syndrome seen in chow diet-fed Vav3–/– mice." (PMID 34571735, 2021). "However, it is worth noting that genetic association studies have found associations of specific VAV2 and VAV3 gene polymorphisms with the development of functions found in mice such as cardiovascular homeostasis, hypertension, obesity, and diabetes." (PMID 34571735, 2021). "Using this approach, we detected rs11863726 in hemoglobin subunit theta 1 (HBQ1), rs328 in lipoprotein lipase (LPL), and rs112984085 in Vav guanine nucleotide exchange factor 3 (VAV3) for T2D and obesity." (PMID 37623486, 2023). "In our study, we observed several highly case-specific variants in genes previously not directly linked to T2D and/or obesity (e.g., TMC8, PCDHA1, PLEKHA5, HBQ1, VAV3, and ADAMTS13)." (PMID 30126146, 2018).
osteosarcoma (4 papers, 2022 to 2025). A usually aggressive malignant bone-forming mesenchymal neoplasm, predominantly affecting adolescents and young adults. "Downregulated VAV3 could inhibit the angiogenesis of osteosarcoma, and inhibited FZD3 can also block the invasion and malignant growth of osteosarcoma cells." (PMID 35340229, 2022). "Thus, this study suggests that the hub nodes LEF1, RUNX2, CSF1R, VAV3, FZD3, CDKN1A, and FBN1 are key factors in the progression of osteosarcoma." (PMID 35340229, 2022).
COVID-19 (3 papers, 2020 to 2025). A disease caused by infection with severe acute respiratory syndrome coronavirus 2. "The top molecules in the COVID-19 T1 and T2 data set with the greatest alteration in methylation compared to healthy controls included hypomethylated MUC20, VAV3, CCL20, and mir21 and hypermethylated GIT2, IFNGR2, FCER1G, and OLR1." (PMID 41227320, 2025). "In COVID-19 non-survivor genes related to neutrophil chemotaxis and migration, including CXCL10, CCL20, CCL8, C3AR1, CCL2, VAV3 are significantly upregulated; increased neutrophil is a typical signature of COVID-19 and closely linked to fatality, as already reported by other studies." (PMID 37949875, 2023).
Hypertension (3 papers, 2021 to 2025). The presence of chronic increased pressure in the systemic arterial system. "VAV3, a regulator of vascular smooth muscle cell proliferation and migration involved in vascular wall remodeling, has been associated with cardiovascular risk factors and an increased risk of developing hypertension." (PMID 38886689, 2024). "These insights not only elucidate cardiovascular disease mechanisms but also highlight potential GEF‐targeted therapies (e.g., against VAV3, ARHGEF1, TIAM1, or PDZ‐RhoGEF) for hypertension, atherosclerosis, and myocardial regeneration." (PMID 41020039, 2025). "The combined used of Vav2–/– and Vav3–/– mice also demonstrated that hypertension does not contribute per se to the development of type II diabetes and metabolic syndrome." (PMID 34571735, 2021).
IgA nephropathy (3 papers, 2022 to 2024). "Other loci associated with IgA nephropathy, such as such as DEFA, TNFSF 13, VAV 3, ITGAM-ITGAX, and PSMB 8, encode proteins involved in maintaining the intestinal mucosal barrier or regulating mucosal immune responses." (PMID 39421866, 2024). "ITGAM–ITGAX (rs11150612, rs11574637), VAV3 rs17019602, CARD9 rs4077515, DEFA (rs2738048, rs10086568), and HORMAD2 rs2412971 are mucosal immune defence polymorphisms, that have an impact on IgA production, described as risk loci for IgA nephropathy (IgAN)." (PMID 37685869, 2023).
leukemia (3 papers, 2009 to 2022). A malignant (clonal) hematologic disorder, involving hematopoietic stem cells and characterized by the presence of primitive or atypical myeloid or lymphoid cells in the bone marrow and the blood. "Whole exome sequencing and copy number variation analyses identified no large-scale mutations or copy number variation in regions containing genes associated with leukemogenesis in the serially propagated WT and Vav3−/− leukemias." (PMID 35650206, 2022). "The persistency of leukemia in vivo in Vav3-/- chimeras suggests that Vav3-/- BCR-ABL1 leukemia has evolved mechanisms of escape relying on RAC-independent pathways such as STAT3 signaling pathways." (PMID 34711926, 2022). "Together, our data show that Vav3-deficient leukemia progenitor cells do not respond to IODVA1 in cellular and in vivo assays while re-introducing VAV3 re-sensitizes them to IODVA1." (PMID 34711926, 2022). "VAV3, a guanine nucleotide exchange factor, is activated and overexpressed in these leukemias." (PMID 35650206, 2022). "Furthermore, we have shown that the exchange activity of Vav3 found in the nucleus is important for the proliferation and progression of p190-BCR-ABL+ leukemia using a PRC1- and to a lesser extent PRC2-dependent mechanism." (PMID 35650206, 2022). "However, we did find a heterozygous point mutation in Pax5 (P80R) in three out of the four analyzed secondary WT leukemias but not in the Vav3−/− leukemias." (PMID 35650206, 2022).
schizophrenia (3 papers, 2014 to 2019). A major psychotic disorder characterized by abnormalities in the perception or expression of reality. "Furthermore, pursuing a preceding Japanese GWAS analysis of schizophrenia, Aleksic and colleagues have revealed VAV3 to be a candidate gene for schizophrenia based on Voxel-Based Morphometry and Mutation Screening." (PMID 30934641, 2019). "Moreover, it was recently found that VAV3 is a candidate gene for schizophrenia, pointing to the importance of investigating Vav3 in the molecular pathophysiology of schizophrenia." (PMID 25879033, 2015).